FOXM1 (forkhead box M1)
Diseases named in the same sentence as FOXM1 in open-access papers (continued):
Sharing a sentence is not in itself a finding about the gene and the disease.
cancer (continued). "Indeed, previous publications reported that knockdown of FOXM1 and ERK could reduce cell growth and invasiveness of human cancers." (PMID 23285101, 2012). "The oncogenic splice isoforms FOXM1B and/or FOXM1C are over-expressed in all carcinomas examined to date, but not in quiescent tissues, suggesting FOXM1 may represent a therapeutic target in many human solid tumor types." (PMID 22761781, 2012). "The transient effect of siRNA knockdown allowed us to focus on the consequence of reduced FOXM1 activity at the time of treatment (mimicking stochastic variation in expression levels that may occur in cancer cells) rather than a permanent change in expression levels." (PMID 40009518, 2025). "However, commercial anti-cancer therapeutics targeting FOXM1 are not yet available." (PMID 37344857, 2023). "Besides MMP9, FOXM1 (Forkhead Box M1) was a component of GO BP categories “negative regulation of the apoptotic process”, “positive regulation of cell proliferation”, and KEGG pathways “transcriptional misregulations in cancer”, and “pathways in cancer”, as well as major upregulated hub gene." (PMID 37373974, 2023). "In contrast, although biotin-labeled TAT-96-116 or TAT-101-121 interacted with the FOXM1 C-terminus, neither of them effectively bound to full-length FOXM1 in the Pulldown experiments, supporting their weak inhibitory effects on cancer cells compared to TAT-106-126." (PMID 37344857, 2023). "Although in these cancers a direct correlation between FOXM1 overexpression and the increase of Nrf2 protein was not investigated, we can postulate that this pathway could also contribute to the overexpression of Nrf2 in such chemoresistant cancers." (PMID 33805928, 2021). "However, how is FOXM1 overexpressed in cancer is not all clear." (PMID 32651364, 2020). "Furthermore, FOXM1 may be a potential therapeutic target in ALK + ALCL, and disruption of the binding between FOXM1 and NPM1 in the NPM-ALK—NPM1 heterodimers may serve as a highly specific anti-cancer therapeutic approach for NPM-ALK + ALCL." (PMID 31390744, 2019). "Furthermore, analysis of BMYB and FOXM1 activity in cancer cells lacking RB and p130 could provide significant insight into the activation of G2/M gene expression when G1/S gene expression is deregulated." (PMID 31667499, 2019). "Targeting FoxM1 over-expressing BC with thiostrepton either accompanied with chemotherapy or as maintenance after chemotherapy maybe beneficial in these aggressive cancers that currently have no identified therapeutic targets that can be targeted for management." (PMID 29707121, 2018). "However, while possessing a clear pro-proliferative nature, FOXM1 is not considered a canonical oncogene, since it has not yet been causally linked to tumor initiation, and it is currently not included in the COSMIC Cancer Gene Census, also due to its lack of cancer-specific somatic mutations." (PMID 39858603, 2025). "In addition, the decreased expression of FOXM1 and SPARC in liver metastases compared to primary tumors may mainly reflect the phenotypic changes associated with metastatic progression rather than other cancer antigens." (PMID 40806530, 2025). "To give a further demonstration, we collected cancers by setting the criteria that both HMGA1 and FOXM1 were no less than two-fold higher and the correlation coefficient was greater than or equal to 0.5." (PMID 37240870, 2023). "An increased protein level of HMGA1 and FOXM1 in LUAD and LIHC cancer tissues was detected compared to normal ones." (PMID 37240870, 2023). "Unlike FOXM1, the FOXO transcription factors are tumor suppressors and are often inactivated in cancers." (PMID 37686402, 2023). "Regarding the multiple biological functions of FOXM1, it has been proven to be a potential therapeutic target for cancer, while there are no FDA-approved FOXM1 targeting drugs in oncology treatment." (PMID 37234166, 2023).
cancer (continued). "We recently identified a small molecule inhibitor of FOXM1, Robert Costa Memorial Drug-1 (RCM1) that decreased tumorigenesis across multiple cancer types, including RMS, and is also non-toxic." (PMID 36816948, 2023). "Studies in other cancers have suggested that the PI3K/AKT pathway, independent of the MAPK/ERK pathway, functions as a main activator of oncogenic FOXM1 activity." (PMID 34205406, 2021). "The role of the Forkhead Box M1 (FoxM1) transcription factor in HCC development has been well documented, however, its involvement in cancer metabolism of HCC has not been fully determined." (PMID 29765517, 2018). "FDI-6 was reported to specifically inhibit the DNA binding activity of FOXM1, but not other FOX family members, and was shown to inhibit cancer cell growth in vitro." (PMID 26243836, 2015). "Surprisingly, there is no follow-up publication in YAP-regulated FOXM1 in any other cell types, in spite of the clear emerging attention to the roles of the Hippo-YAP pathway in various cancers." (PMID 26299613, 2015). "Notably, along with our study, we found that expression of p-RPS6, E2F1, FOXM1, and WEE1 protein was elevated significantly in de-differentiated LPS cancer cells, relative to nonmalignant ASC52telo cells." (PMID 33564073, 2021). "We therefore examined the total number of cancer-specific enhancer links in samples with and without KRAS or EGFR genetic alterations and in the highest quartile and remaining quartiles of expression of FOXM1 and MYBL2, respectively." (PMID 32925947, 2020). "Since PIMA is a particularly aggressive cancer subtype without specific therapeutic options, our findings suggest that pharmacological inhibition of either AGR2 or its upstream regulator, FOXM1, may be beneficial for PIMA patients." (PMID 29267283, 2017). "The majority of the FOXM1 target genes that we have discovered and investigated in the context of OAC are novel target genes and have not been extensively studied in the context of cancer." (PMID 25889361, 2015). "Notably, forkhead box M1 (FOXM1) was overexpressed in both epithelial and clear-cell EOC tissues, potentially serving as a negative indicator of non-serous EOC patient outcomes, and promoted cancer progression in all platinum-resistant EOC patients." (PMID 34631583, 2021). "In contrast, other cancer types lacked FOXM1 amplification but had FOXM1 expression at or above the pan-cancer median (e.g., CESC, DLBC), indicating that additional genetic alterations may contribute to increased FOXM1 expression in cancer." (PMID 30795624, 2019).
tumor (857 papers, 2008 to 2026). "For instance, genes such as AURKA, APEX2, CCNE1, and FOXM1 have been reported to be associated with tumor resistance." (PMID 40098976, 2025). "The STIL then translocates to the nucleus and associates with FOXM1, promoting tumor metastasis and stemness." (PMID 40377005, 2025). "This antitumor effect has been mainly attributed to the inhibition of FOXM1 in tumor cells by thiostrepton, which causes cell cycle arrest and impaired proliferation." (PMID 40820379, 2025). "The analysis revealed that FOXM1 expression was closely associated with the stage of OC and the malignant invasive tumor phenotype." (PMID 40612352, 2025). "Conversely, knocking down CKS1B in BxPC-3 and CFPAC-1 cells overexpressing FOXM1 demonstrated that CKS1B knockdown reversed the enhanced tumor growth, migration, and CSCs self-renewal associated with FOXM1 overexpression." (PMID 39897042, 2025). "It achieves this by promoting the production of tumor-related gene variants in an m6A-dependent manner, specifically by regulating the exon skipping of FOXM1 through its m6A-modified motif." (PMID 41429980, 2025). "To gain further insight into the mechanism underlying β‐sitosterol's inhibitory effects on tumour growth and metastasis in vivo, we assessed the expression of FOXM1 in tumour tissues using qPCR, IHC and western blotting." (PMID 38063438, 2024). "In in vitro study using KS-EMPD-1, FOXM1 was associated with tumor cell viability, migration, and invasiveness, and its inhibition strongly impaired tumor cell viability." (PMID 38374400, 2024). "Upregulation of FOXM1 was shown to be common in EAC tumor samples and associated with poor survival outcomes." (PMID 38373993, 2024). "FOXM1 drives cell proliferation, invasion, metastasis, drug resistance, and tumor growth and progression, and its expression is associated with poor prognosis and shorter patient survival." (PMID 39594778, 2024). "We further performed xenograft assays in immunodeficient mice and confirmed that loss of FOXM1 led to a substantial inhibition of tumor growth in vivo." (PMID 38373993, 2024). "It has also been demonstrated that in addition to high levels of FOXM1 in tumor cells, FOXM1 is also highly expressed in immunosuppressive tumor-associated macrophages (TAMs)." (PMID 38398147, 2024). "FOXM1 expression is also associated with a larger tumor size, lymphovascular invasion, lymph node metastasis, and a higher stage in ER+ hormone therapy-resistant breast cancer." (PMID 39594778, 2024). "Using syngeneic murine models, we found that loss of FOXM1 resulted in heightened infiltration of CD8+ T cells into the tumor microenvironment, which was corroborated by in vitro CD8+ T cell chemotaxis assays." (PMID 38373993, 2024). "Previous studies have shown that the loss of FOXM1 in tumor cells results in decreased tumor cell proliferation, metastasis, angiogenesis, and increased tumor cell death." (PMID 36816948, 2023). "Treatment with a cell-permeable ARF26-44 peptide (FOXM1 inhibitor) decreased angiogenesis and tumor cell development and caused a consequential escalation in cell death within the HCC region but not in the surrounding healthy liver tissue." (PMID 37626655, 2023). "As such, knockdown of FOXM1 increases the expression of p16INK4a and other CDK inhibitors, whereas FOXM1 overexpression suppresses their transcription and causes elevated activity of tumor-promoting CDK2 and CDK4/6." (PMID 37686402, 2023). "IHC assay displayed that a number of infiltrated neutrophils in the tumor microenvironment were positively associated with the expression of FOXM1 in EC." (PMID 37159818, 2023). "FOXM1 has been implicated as an oncogene and regulates multiple aspects of oncogenesis, including tumor cell growth, epithelial-to-mesenchymal transition (EMT), angiogenesis, metastasis, drug resistance, immunosuppression, and so on." (PMID 37759731, 2023).
tumor (continued). "In gliomas, PHGDH interacts with the N-terminus of FoxM1 to hinder its ubiquitination, thus causing degradation of the proteasome and promoting the proliferation of tumor cells." (PMID 35344765, 2022). "A subset of STIL translocate into nucleus and associate with FOXM1 (Forkhead box protein M1) to promote tumor metastasis and stemness via FOXM1-mediated downstream target genes." (PMID 35365182, 2022). "We further demonstrated that a subset of STIL translocate into nucleus and associate with FOXM1 to promote tumor metastasis and CS via FOXM1-mediated downstream target genes." (PMID 35365182, 2022). "Another study of 119 OSCC patients suggests a role of forkhead box protein M1 (FOXM1) to be associated with tumor recurrence." (PMID 35207438, 2022). "FOXM1-high HCC was also significantly associated with macroscopic tumor thrombosis and advanced BCLC stages." (PMID 35955438, 2022). "FOXM1 is, therefore, implicated in the process of tumor invasion, which is a hallmark of GBM as well." (PMID 34948433, 2021). "Downstream of AVIL, FOXM1 is implicated in angiogenesis, tumor invasion, and EMT, while LIN28B allows expression of oncogenes by inhibiting let-7 miRNAs." (PMID 34948433, 2021). "A ROC curve analysis showed FOXM1 has very good diagnostic performance with AUC = 0.8909 and with the cutoff value of 104.67, the sensitivity and specificity for detecting tumor aggressiveness was 95% and 87%, respectively." (PMID 34885040, 2021). "FOXM1 mRNA expression associates with higher EOC tumor grades and stages, and FOXM1 protein expression associates with EOC lymph node metastasis and a higher FIGO stage." (PMID 34205406, 2021). "Second, FoxM1 is associated with tumor cell proliferation, migration, invasion, and angiogenesis, suggesting that FoxM1 is an oncogenic factor." (PMID 35153742, 2021). "In nasopharyngeal carcinoma, FoxM1 is significantly associated with stem cell-related clinicopathological features, including advanced clinical stages, tumor recurrence, and distant metastases." (PMID 33588867, 2021). "High FOXM1 levels are generally associated with chemoresistance of malignant cells, aggressive tumor phenotype, and poor prognosis due to decreased efficacy of common therapeutic strategies." (PMID 34381718, 2021). "FoxM1 is intimately implicated in tumor recurrence of different malignancies while its down-regulation has been shown to sensitize resistant tumor cells to therapy." (PMID 34900697, 2021). "Functional study revealed PTTG3P promote tumor growth and metastasis via functioning as a ceRNA for miR-132/212-3p, thereby preventing its association with target FoxM1 mRNA." (PMID 33298873, 2020). "Owing to the over-expression of β-catenin, which has been associated with tumor progression and the involvement of FOXM1 in the translocation of β-catenin to the nucleus, the effect of FAM188B knockdown on β-catenin expression was tested." (PMID 33142744, 2020). "In 2011, Priller and colleagues showed that FOXM1 is significantly upregulated in MB cell lines and tumor tissue and linked the high expression level of FOXM1 to an unfavorable patient outcome." (PMID 31541075, 2019). "On the other hand, overexpressed FOXM1 can recruit tumour associated macrophages (TAM), which can also secrete TGF-β1 and promote tumour cell invasion." (PMID 31554904, 2019). "In the MetB subtype, androgen‐stimulated gene expression is generally low, tumor cells are dedifferentiated, and cell proliferation is high, in parallel with transcript levels of the proliferation‐associated transcription factor FOXM1." (PMID 31162796, 2019). "Over-expression of FSCN1 or FOXM1 was associated with the tumour microenvironment and immune signatures in ACCs." (PMID 31783819, 2019).
tumor (continued). "In a wide range of cancers, including GBM, elevated expression of FoxM1 is well recognized and it is strongly linked to tumor malignancy, angiogenesis, and invasiveness." (PMID 29700308, 2018). "FOXM1 has previously been associated with various clinical characteristics in BC, such as tumor stage and nodal status, ER+ status as well as TN subtype." (PMID 30572639, 2018). "Accumulating evidence has shown the role of the PI3K/Akt pathway in the mechanisms of EPS8 associated tumor proliferation, survival and drug resistance by activating downstream targets, such as FOXM1, mTOR, MMP-9 and caspase-9." (PMID 29357910, 2018). "Since FOXM1 targets were also enriched in the tumor samples based on ENCODE ChIP-seq data, we also compared to a FOXM1 target gene set identified by ChIP-seq." (PMID 29782499, 2018). "Deletion of Foxm1 from respiratory epithelial cells blocked tumorigenesis by oncogenic KrasG12D, and decreased the tumor initiation and growth of Kras-mutations-associated chemically-induced mouse lung tumors." (PMID 29267283, 2017). "We investigated the association between FOXM1 protein and patients’ survival in relation to their tumor histology and sensitivity to platinum-based therapy." (PMID 28482906, 2017). "Similar to intra-tracheal administration, a direct inoculation of FOXM1-deficient A549 cells into the left lung lobe inhibited the tumor growth and metastasis into the liver and mediastinal lymph nodes." (PMID 29267283, 2017). "Hereafter, we discussed the role of FoxM1 in the four tumor types where we found statistically significant association of FoxM1 expression and poor prognosis." (PMID 28770020, 2017). "Altogether, expression of activated FoxM1-ΔN in benign lung adenomas caused tumor progression into poorly differentiated, metastatic adenocarcinomas." (PMID 29267283, 2017). "Molecular studies revealed the activation of MAPK kinases and FoxM1 after loss of GPC3 in tumor cells." (PMID 27259271, 2016). "FOXM1 has been implicated to play a role in cell proliferation, cell cycle control, DNA damage and repair, tumor development and progression, and chemotherapy." (PMID 26588055, 2016). "Regarding the selection of HCC-associated tumor antigens, we have identified FoxM1 as a potential target for immunotherapy." (PMID 27351282, 2016). "In FOXM1 transgene model, elevated tumor formation was associated with persistent pulmonary inflammation, macrophage infiltration and increased expressions of CXCL5, CXCL1 and CCL3." (PMID 25788272, 2015). "We found that FOXM1 is strongly associated with tumor differentiation and occurrence of metastases in gastrointestinal NENs." (PMID 25797272, 2015). "Emerging evidences suggest that many EMT-inducing transcription factors such as Snail and ZEB1 have been found to be associated with expression of FOXM1, which leads to tumor aggressiveness and metastasis." (PMID 25935853, 2015). "Among the most heavily tumor-associated genes was FOXM1, for which the mRNA levels are upregulated in 93% of patient tumors (95% CIBonf: 87%-97%)." (PMID 26555223, 2015). "FoxM1 signaling has been implicated to be associated with carcinogenesis of tumor development in CRC as well as other solid tumors." (PMID 26159723, 2015). "The present study suggested that FOXM1 expression was closely associated with increased tumor invasion, migration and metastasis." (PMID 24885308, 2014). "To further explore this association, we performed co-expression analysis comparing mRNA levels of FOXM1 to those of the 70 synergy-associated downregulated transcripts in 6466 primary tumor samples of diverse tissue origins." (PMID 24810962, 2014). "In human HCC cases, FOXM1 protein overexpression was highly associated with increased tumor grade and advanced tumor stage." (PMID 24325450, 2013). "FOXM1 is implicated in the tumourigenesis of more than 20 types of human tumours and contributes to both tumour initiation and progression." (PMID 21314937, 2011).